MTOR (mechanistic target of rapamycin kinase)
Diseases named in the same sentence as MTOR in open-access papers (continued):
Sharing a sentence is not in itself a finding about the gene and the disease.
glomerulosclerosis (26 papers, 2014 to 2025). A hardening of the kidney glomerulus caused by scarring of the blood vessels. "This over-active mTOR is directly related to unbalanced glomerular epithelia hypertrophy, podocyte effacement then glomerulosclerosis which precede irreversible nephron’s loss of function." (PMID 36476132, 2022). "Taken together, these data indicate that Rac1-associated mTOR activation in podocytes plays an important role in preventing the kidneys from developing glomerulosclerosis." (PMID 29567961, 2018). "In agreement, mTOR inhibition has been associated with amelioration of kidney fibrosis, glomerulosclerosis and interstitial inflammation, having an important role in renal disease." (PMID 24853130, 2014). "In agreement, mTOR inhibition has been associated with amelioration of kidney fibrosis, glomerulosclerosis, and interstitial inflammation, having an important role in distinct renal diseases." (PMID 24971338, 2014). "Recent studies have shown that complete ablation/inhibition of mTORC1 in podocytes resulted in increased vulnerability and glomerulosclerosis, in contrast to the reported therapeutic health benefits of mTOR inhibitors or just genetic lowering of mTOR level." (PMID 36787250, 2023). "In the kidney, several studies have outlined the importance of mTOR signaling in the maintenance of podocyte integrity, primarily through regulation of autophagy, as deletion of either of one of the two mTOR functional complexes resulted in glomerulosclerosis." (PMID 33916159, 2021). "The absence of CD44 in aged null mice was accompanied by reduced glomerulosclerosis, glomerular hypertrophy, mTOR activation, and PEC activation, supporting a probable role for CD44 in kidney aging." (PMID 32597007, 2020). "Rac1 and mTOR require each other to maintain homeostasis in podocytes and exhibit potential as therapeutic targets for glomerulosclerosis." (PMID 29567961, 2018). "Paradoxically, rapamycin is known to induce renal dysfunction by suppressing mTOR, and amTOR knockout mice reportedly develop proteinuria and glomerular sclerosis as they age43." (PMID 29348412, 2018). "Inhibition of mTOR by rapamycin in the setting of adaptive hypertrophy results in proteinuria and glomerulosclerosis, whereas inhibition of mTOR in the setting of maladaptive hypertrophy could be of therapeutic benefit." (PMID 40698593, 2025). "BM-MSCs-EXOs can also induce glomerular sclerosis by activating the PI3K/Akt/mTOR pathway." (PMID 36363614, 2022). "Inhibition of mTOR activation reduces proteinuria and glomerulosclerosis, but complete reduction in mTOR activity may lead to glomerular disease progression, indicating that the therapeutic window of the drug is narrow." (PMID 36003509, 2022). "Moreover, while remaining podocytes can increase their mTOR activity following podocyte depletion at younger ages, by 18 months of age they cannot and marked proteinuria and glomerulosclerosis ensue." (PMID 35290515, 2022). "mTOR-mediated podocyte hypertrophy during podocyte loss seems to be crucial to maintain glomerular functional integrity, as pharmacological mTOR-inhibition during acute podocyte loss resulted in albuminuria, PEC-activation and glomerulosclerosis in mice." (PMID 35095882, 2021). "To evaluate whether mTOR inhibition can attenuate the progression of glomerulosclerosis in a later phase of disease development, we performed an experiment treating anti-Thy1.1 mice daily with sirolimus or phosal for a period of 20 days." (PMID 32444668, 2020). "Progression of glomerulosclerosis in DN and podocyte injury could be hindered by genetically inhibiting the activation of mTOR." (PMID 33097050, 2020). "Our findings suggest that C/EBPα knockout in podocytes aggravates podocyte senescence through the AMPK/mTOR pathway, leading to glomerulosclerosis, and that subsequent albuminuria exacerbates the epithelial–mesenchymal transdifferentiation of senescent tubular cells by suppressing autophagy." (PMID 31527620, 2019).
glomerulosclerosis (continued). "In summary, our data demonstrate that, in injured podocytes, the presence of Rac1 promotes mTOR activation so that remaining podocytes could maintain their size to protect the kidneys from developing glomerulosclerosis." (PMID 29567961, 2018). "Urinary mTOR expression was correlated with score of tubulointerstitial fibrosis (TIF) and score of glomerular sclerosis." (PMID 31485275, 2019). "Our findings point out that an elevated mTOR expression in parietal epithelial cells might contribute to PEC activation and the formation of glomerulosclerosis." (PMID 32444668, 2020). "In summary, we demonstrated that in CD44−/− mice, the lack of functional CD44, limited age‐related increases in segmental and global glomerulosclerosis, glomerular hypertrophy, an increase in Bowman's capsule length, changes in the PEC phenotype, PEC ERK activation, and mTOR activation." (PMID 32597007, 2020). "In this study, we tested the hypothesis that mTOR signalling regulates PEC activation and that mTOR inhibition may prevent PEC proliferation and subsequently glomerulosclerosis in the anti-Thy1.1 mouse model, an experimental model of collapsing FSGS." (PMID 32444668, 2020). "Therefore, mTOR might be a pharmaceutical target to prevent or reduce PEC activation and subsequently glomerulosclerosis formation." (PMID 32444668, 2020).
leiomyosarcoma (26 papers, 2012 to 2025). An uncommon, aggressive malignant smooth muscle neoplasm, usually occurring in post-menopausal women. "In our experimental conditions, we observed a similar effect; trabectedin treatment increases the phosphorylation of the ribosomal protein S6, an effect that is avoided by treating leiomyosarcoma cells with mTOR inhibitor rapamycin." (PMID 38758230, 2024). "We found that aberrant PI3K/mTOR signalling fosters an immunosuppressive tumour microenvironment and contributes to immune checkpoint blockade resistance in uterine leiomyosarcoma." (PMID 38711203, 2024). "The inhibition of mTOR, sensitized leiomyosarcoma cultures for trabectedin treatment, increasing cell death." (PMID 38758230, 2024). "In this case, the combination of rapamycin (i.e. mTOR inhibitor) plus trabectedin was performed as a proof of concept in leiomyosarcoma in vitro models." (PMID 38758230, 2024). "A 48-year-old female with metastatic leiomyosarcoma and TSC2 mutation enrolled onto a mTOR inhibitor trial 2 days after her report was viewed in MatchMiner by the trial team." (PMID 36202909, 2022). "Leiomyosarcoma cell line (MES-SA) appeared as the most sensitive to both mTOR inhibitors among all of tested cell lines." (PMID 33173419, 2020). "We report an original study assessing the respective in vitro and in vivo effects of a drug panel targeting different components of the PI3K/AKT/mTOR pathway on human leiomyosarcoma, an extremely rare form of cancer." (PMID 28002802, 2017). "Our pre-clinical results suggest that dual targeting of the PI3K/AKT/mTOR pathway in combination with MAPK inhibition is a promising therapeutic strategy against leiomyosarcoma." (PMID 28002802, 2017). "Of note, a new generation of mTOR-targeting agents were found to be effective in a preclinical model of leiomyosarcoma." (PMID 29156702, 2017). "In summary, this study supports further investigation into the use of PI3K and mTOR inhibitors alone and in combination with standard treatment in leiomyosarcoma patients." (PMID 26952093, 2016). "This possibility is consistent with the leiomyosarcoma formation seen when PI3K/mTOR signaling is inappropriately activated in smooth muscle cells by deletion of the negative regulator, PTEN." (PMID 26555296, 2015). "Activation of the TRIO–RAC–RICTOR–mTOR signaling by the α10 subunit promotes tumor cell survival, and inhibitors of RAC and mTOR have shown anti-tumor effects in vivo, providing a potential therapeutic strategy for high-risk leiomyosarcoma patients." (PMID 37932738, 2023). "Leiomyosarcoma cell line (MES-SA) was found sensitive to both mTOR inhibitors." (PMID 33173419, 2020). "Thus, we decided to further investigate the effects of combined targeting of the MAPK and PI3K/AKT/mTOR signaling cascades in leiomyosarcoma cells." (PMID 28002802, 2017). "The PI3K/AKT/mTOR pathway plays a crucial role in the development of leiomyosarcomas (LMSs)." (PMID 28002802, 2017). "One patient had a leiomyosarcoma, where alterations of the mTOR pathway have been described, such as the overexpression of RICTOR, a major component of the mTOR complex 2, which might contribute to the pathogenesis of well-differentiated leiomyosarcoma." (PMID 24216984, 2013). "Furthermore, the fact that GEM is widely accepted therapeutic option in uterine leiomyosarcoma may simplify designing of future clinical trials aimed to assess the efficacy of addition mTOR inhibitor to such standard treatment." (PMID 33173419, 2020). "For example, Babichev Y. with colleagues demonstrated a high potency of PI3K vs. mTOR inhibitors used in combination of doxorubicin against LMS in vitro and in the leiomyosarcoma xenografts." (PMID 33266502, 2020).
leiomyosarcoma (continued). "Leiomyosarcoma (LMS) is one of the most frequent soft tissue sarcoma subtypes and is characterized by a consistent deregulation of the PI3K/mTOR pathway." (PMID 30683135, 2019). "Activated MTOR/AKT1 signaling, RASSF1 hypermethylation and MYC expression can also be found in a subset of leiomyosarcomas." (PMID 29881541, 2018). "Here, we report an original study investigating the effects of dual inhibition of PI3K and mTOR in human leiomyosarcomas on anti-tumor activity, especially the biological consequences on components of the PI3K/AKT/mTOR and RAS/MEK/ERK pathways." (PMID 28002802, 2017). "Among the scarce clinical reports on targeted treatments in uterine leiomyosarcoma patients, a promising approach involves tackling the PI3K/AKT/mTOR pathway." (PMID 26576131, 2015). "Based on clinical reports, promising approaches for uterine leiomyosarcoma patients include inhibition of VEGF and mTOR signaling, preferably in combination with other targeted or cytotoxic compounds." (PMID 26576131, 2015). "In addition, it has been shown that EZH2 inhibition is able to suppress leiomyosarcoma CSCs proprieties and retrieve the anti-tumor effect of PI3K/mTOR inhibition, supporting the therapeutic value of this combination." (PMID 32532153, 2020).
Myocardial fibrosis (26 papers, 2009 to 2025). "The PI3K/Akt‐mTOR pathway is associated with the occurrence of myocardial fibrosis and has a regulatory effect on the proliferation and migration of cardiac fibroblasts." (PMID 32881330, 2020). "QSYQ activates autophagy in rat cardiomyocytes by regulating the PI3K/Akt-mTOR pathway and exert an anti-reactive myocardial fibrosis effect." (PMID 33582656, 2021). "In conclusion, our results have revealed that QSYQ impacts anti-reactive myocardial fibrosis in a dose-dependent mechanism which is mediated by the activation of myocardial autophagy via the PI3K/AKT/mTOR pathway." (PMID 33582656, 2021). "The data indicate that depletion of MEF2C is sufficient to markedly attenuate the hypertrophic growth and myocardial fibrosis of overloaded left ventricle by a mechanism dependent on defective activation of mTOR/S6K pathway." (PMID 20041152, 2009). "After Dox and Ang II treatment, SLP-2 deficiency further aggravated myocardial fibrosis, increased myocardial oxidative stress and apoptosis, and activated autophagy by inhibiting PI3K-Akt-mTOR signaling pathway, ultimately exacerbating adverse cardiac remodeling." (PMID 36788223, 2023). "In summary, we first demonstrated that MC-LR may induce myocardial fibrosis by activating the PI3K/AKT/mTOR signaling pathway." (PMID 37505696, 2023). "In addition, we provided evidence that circulating exosomes derived from untreated OSA patients increased myocardial fibrosis and hypertrophy by inhibiting autophagy through the Akt/mTOR signaling pathway." (PMID 35321104, 2022). "In a myocardial fibrosis model, AMPK activity is significantly reduced compared to the normal state, while mTOR activation has been markedly enhanced." (PMID 40002810, 2025). "The key markers of myocardial fibrosis, nitro-oxidative stress, inflammation, apoptosis, autophagy, and AMPK/mTOR signaling were examined." (PMID 37386620, 2023). "Therefore, our results indicate that lower LAT1 can improve mitochondrial dysfunction and relieve apoptosis and myocardial fibrosis via the mTOR/Bax/Bcl-2/caspase-3 signaling pathway, and there was a positive feedback loop between LAT1 and mTOR." (PMID 39182099, 2024).
Rett syndrome (26 papers, 2013 to 2025). A severe neurodevelopmental disorder affecting the central nervous system. "The mTORC1 (mechanistic target of rapamycin (mTOR) complex 1) pathway is differentially regulated in Rett syndrome and other syndromes associated with ASD." (PMID 34827633, 2021). "Downregulation of mTOR activity is thought to play an essential role in the pathogenesis of neurodevelopmental disorders such as Rett syndrome and Cyclin-Dependent Kinase Like 5 (CDKL5) deficiency disorder." (PMID 34204880, 2021). "The opposite is also true; low levels of PI3K/Akt/mTOR activity are linked with Rett syndrome (RTT), a rare case of autism-associated disease." (PMID 26877878, 2016). "Both morphological phenotypes and protein synthesis defects in the mutant neurons were rescued with genetic activation of the mTOR pathway, highlighting the possible role of the mTOR pathway in Rett Syndrome." (PMID 35359577, 2022). "Our findings are consistent with previous reports of reduced mTOR pathway in Rett syndrome and decreased Akt total protein and phosphorylation in frontal cerebral cortex from autistic patients." (PMID 25627160, 2015). "mTOR hypoactivity was one characteristic of a mouse model for Rett syndrome." (PMID 34204880, 2021). "In Rett syndrome, miR-199 is a positive regulator of the mTOR pathway activity." (PMID 30881383, 2019).
uveal melanoma (26 papers, 2012 to 2025). A melanoma derived from melanocytes of the uveal tract. "Knock down of Beclin1 or ATG5, or expression of an activated form of mTOR, significantly reduced uveal melanoma cell killing." (PMID 38758815, 2024). "Farhanet al.57 discovered that Artemisinin regulated migration and invasion of uveal melanoma through PI3K/AKT/mTOR pathway." (PMID 38253629, 2024). "We then determined that inhibitors of FASN and mTOR led to the suppression of uveal melanoma cell growth." (PMID 37444561, 2023). "Inhibition of CHAC1, an early ferroptosis mediator, decreases the cell viability of uveal melanoma cells by inactivating AKT/mTOR." (PMID 36139919, 2022). "Inhibition of the PI3K/AKT/mTOR pathway has been reported to be strongly suggested as a therapeutic potential for the prevention and treatment of uveal melanoma." (PMID 36081847, 2022). "Taken together, this demonstrates that the combination of romidepsin, administered in a clinically relevant manner, with an mTOR inhibitor increases cell death in uveal melanoma cell line models." (PMID 34533562, 2021). "In this study, we demonstrate that combining romidepsin, administered in a manner consistent with the clinical application of the drug, with an mTOR inhibitor increases cell death in uveal melanoma cell lines." (PMID 34533562, 2021). "Due to its high degree of efficacy in all of the four uveal melanoma cell line models, we chose to further examine the combination of romidepsin with mTOR inhibitors in the cell line models." (PMID 34533562, 2021). "Combining the mTOR inhibitor rapamycin with the PI3K inhibitor GDC-0941 was found to lead to increased apoptosis in uveal melanoma cell lines as well as patient-derived xenografts." (PMID 34533562, 2021). "An inhibitor of protein kinase C combined with an inhibitor of the mTOR pathway has also been found to be efficacious for uveal melanoma." (PMID 34533562, 2021). "Activation of MAPK and AKT/mTOR pathways was found in a series of uveal melanomas, but in those cancers this activation did not relate with the presence of GNAQ mutation." (PMID 23904987, 2013). "We investigated the impact of dual pathway inhibition with the MEK1/2 inhibitor selumetinib and the mTOR kinase inhibitor AZD8055 upon uveal melanoma cell lines of distinct tumor genotypes." (PMID 22808163, 2012). "MDK activates mTOR by phosphorylating mTOR target RPS6 in uveal melanoma cells." (PMID 37240085, 2023). "To analyze gene transcriptional changes that might contribute to toxicity of romidepsin/mTOR inhibitor combinations, we performed RNA sequencing analysis of the uveal melanoma cell line Mel202." (PMID 34533562, 2021). "The mTOR pathway is one of the many survival pathways activated by pathogenic variants in the GNAQ or GNA11 genes, supporting the need for investigations into the efficacy of therapies for uveal melanoma containing mTOR inhibitors." (PMID 34533562, 2021). "Our data suggest that romidepsin in combination with mTOR inhibition could be an effective treatment strategy against uveal melanoma due in part to changes in apoptotic proteins." (PMID 34533562, 2021). "High rates of loss of heterozygosity (LOH) at the phosphatase and tensin homolog (PTEN) (a negative regulator of the PI3K/AKT/mTOR pathway) locus and mutations within the PTEN coding region translates to more than half of uveal melanomas having decreased or complete loss of PTEN expression." (PMID 22808163, 2012). "In addition, HIF-1α protein stabilization and the increased expression of its target gene, VEGF, was evident in uveal melanoma cells through a mTOR-dependent mechanism, and was shown to promote the invasive capacity of uveal melanoma cells through the AKT signaling pathway." (PMID 34199959, 2021). "However, our current study found that mTOR inhibition combined with HDAC inhibition was effective in uveal melanoma cell lines, which may represent another treatment for this disease." (PMID 34533562, 2021).